CCL2 (C-C motif chemokine ligand 2)
Diseases named in the same sentence as CCL2 in open-access papers (continued):
Sharing a sentence is not in itself a finding about the gene and the disease.
tumor (continued). "Alternatively, our findings in the HCC environment could be explained by an indirect, secondary effect due to reduced tumour load of Ccne1-depleted mice, independent of CCL2-driven chemotaxis or T cell-mediated activation via INFG." (PMID 34830835, 2021). "The anti-tumor “N1” phenotype exhibited increased tumor cytotoxicity, elevated expression of CXCL13, CCL3, CCL6, CXCL10, TNFα and ICAM-1 and low ARG1 content, while the pro-tumor “N2” neutrophils expressed high levels of ARG1, MMP9, VEGF and several cytokines, including CCL2, CCL5, CCL17 and CXCL4." (PMID 34572138, 2021). "Preclinical evidence showed that tumor and stroma cells release C–C motif chemokine ligand 2 (CCL2) to recruit monocytes expressing C-C chemokine receptor type 2 (CCR2); these recruited CCR2-expressing monocytes will finally polarize into TAMs, contributing to tumor cell survival." (PMID 33916915, 2021). "We did not observe any changes in either tumor growth or MCP-1/CCL2 levels." (PMID 33419021, 2021). "In LLC xenograft mice, endostatin inhibited tumor angiogenesis by reducing the number of CD31+ cells and VEGF expression, aggravated hypoxia, and increased levels of inflammatory cytokines (IL-4, IL-6, IL-10) in tumor and CCL2 expression in endothelial cells and fibroblasts." (PMID 34209679, 2021). "Studies have shown that CCR2+ TAMs, CAFs, and cancer-associated adipocytes serve as additional sources of CCL2; these findings demonstrate the non-canonical roles of CCL2 in fibrosis generation, mesenchymal–epithelial transition, paracrine-induced tumor invasion, and angiogenesis." (PMID 34386431, 2021). "However, in the clinic, completion of a Phase II clinical trial using anti-CCL2 antibodies in castration-resistant prostate cancer found that treatment neither blocked the signaling axis nor did it reduce tumor burden." (PMID 33924237, 2021). "Increased secretion of IL-6, TNFα, CCL2, CCL5, CXCL9 and GM-CSF, which are pro-inflammatory factors combined with decreased secretion of anti-inflammatory factors including IL-4, IL-28A, CCL24, CXCL12 and SCF from infected HEL299 fibroblasts, is expected to be tumor-promoting and enhance metastasis." (PMID 34575976, 2021). "However, there is some evidence that CCL2 can also have some suppressive effects on tumor development through recruitment of T cells that mediate anti-tumor immunity, although these effects of CCL2 have not been studied extensively." (PMID 34771552, 2021). "Thanks to the production of pro-inflammatory factors, such as CCL2, IL-8, CCL3, and IL-6, and their crosstalk with activated T cells, TANs, in early-stage human lung cancer, are actively involved in the stimulation of T cells responses limiting tumor progression." (PMID 33418996, 2021). "Similarly, co-expression of Cxcl1 and Ccl2 in 889-S1 tumour cells substantially increased tumour incidence and growth in the presence of USP12 overexpression, suggesting the importance of the tumour-extrinsic effects controlled by USP12." (PMID 34381028, 2021). "In addition, CCL2 also binds another receptor CCR4, chemokine (C–C motif) receptor 4, expressed on cytotoxic T lymphocytes, which results in regulating the migration and infiltration of T regulatory cells to tumor sites." (PMID 33230600, 2021). "Many preclinical studies showed high efficacy of CCL2/CCR2 antagonists, e.g., in the mouse model of lung adenocarcinoma, targeting CCR2 with a small molecule inhibitor not only reduced recruitment of M2-type macrophages but also induced tumor infiltration of activated CD8+ T cells." (PMID 33919517, 2021). "CCL2 or MCP-1 is an inflammatory cytokine produced by osteoblasts, osteoclasts, tumor, endothelial, and stromal cells, and is further stimulated within the TMA by bone marrow adiposity, inflammation, and the presence of tumor cells or tumor-derived factors such as PTHrP." (PMID 34064859, 2021).
tumor (continued). "In HCC tumor microenvironment, several cytokines and chemokines such as CXCL1, CSF1, CCL2, CCL9, IL-6, and IL-18 etc., which were secreted from either HCC cells or immune cells, promotes the recruitment and infiltration of MDSCs from the bone marrow into HCC tumor site 32-34." (PMID 33897880, 2021). "Similarly, in an open‐label, multicentre phase Ib study (NCT01204996), researchers found that carlumab sequestered CCL2 for only a short time and did not generate obvious anti‐tumour responses." (PMID 34464477, 2021). "Importantly, some of the cytokines and chemokines upregulated in the tumor were also elevated in the plasma of mice receiving heterologous KV vaccine, including increased levels of IFN-γ, CCL5, CXCL10, CCL2, IL-6, CXCL1, and IL-1β one day after VSV-GP-HPV boost." (PMID 34465781, 2021). "Interestingly, although hypoxia prevents the infiltration of T cells, it stimulates tumor cells to release a large number of macrophage-recruiting factors, such as CCL2, CSF-1, and VEGF, resulting in pronounced enrichment of macrophages in hypoxic tumor regions." (PMID 35070992, 2021). "However, we also found that in CCL2 knockout mice, tumor-originated derived exosomes did not play the same role, which indicated that BC-derived exosomes used CCL2 to construct the pre-metastasis niche." (PMID 34249913, 2021). "Three immune cell markers, the chemokine CC motif ligand 2 (CCL2), the pan macrophage marker CD68, and the M2 macrophage marker CD163, were examined using immunohistochemistry to determine their predictive value for chemotherapy responses in different nodal stage and tumor stage subgroups." (PMID 33467469, 2021). "LMW– and O–HA also promote expression of pro–inflammatory cytokines such as CCL2, which attract pro–tumorigenic circulating monocytes and stromal cells into the tumor microenvironment, and ECM regulators that support pro–tumor immunogenic and fibrogenic functions." (PMID 34827550, 2021). "Based on tumor purity, we ascertained that most cytokines are secreted by TAMs and M2 macrophages, and marker sets have significant correlations with CDH11 in STAD, with examples including CCL-2, TGFB1, CXCL12, and MPP2 of TAMs and IL-10, IL1R1, CD163, and MRC1 of M2 phenotype (P < 0.0001)." (PMID 32685527, 2020). "However, carlumab (CNTO 888) is well-tolerated in phase 2 trial (NCT00992186) but does not block the CCL2/CCR2 axis or show anti-tumor activity as a single agent in metastatic castration-resistant prostate cancer (CRPC)." (PMID 33224886, 2020). "However, through the same mechanisms of CCL2/CCR2 inhibition, ACKR2 was also reported to prevent the activities of beneficial leukocyte sub-populations, such as NK cells and neutrophils that are cytotoxic against tumor cells." (PMID 32582148, 2020). "Furthermore, as cytokines can assist tumor progression, targeting IL-4, IL-13, IL-10, TGF-β, and CXCL5 or enhancing IFN-γ and some chemokines (e.g., CCL2, CCL3, CXCL9, CXCL10) may inhibit tumor invasion and metastasis." (PMID 32346605, 2020). "In accordance, the presence of tumor-infiltrating lymphocytes (TILs) within ILP tumor biopsies, as determined by flow cytometry, correlated positively with the intratumoral levels of the chemokine CCL2, as measured in supernatants of single cell tumor biopsy suspensions." (PMID 32002296, 2020). "Moreover, IL-1β, CCL2, PGE2, among other chemotactic factors, attract natural immunosuppressive cells, including T regulatory (Tregs), myeloid-derived suppressor cells (MDSCs), and M2 macrophages, to the tumor microenvironment." (PMID 32555170, 2020). "Furthermore, CCL2, IL17, and IL18, which are increased in peripheral blood and tumor tissues, may recruit MDSC into tumor tissues." (PMID 32707869, 2020).
tumor (continued). "Pathology studies of tumor tissues detected increased number of TAMs in tumors grown in Fpr2 KO mice and the macrophages isolated from Fpr2 KO mice showed a more-potent chemotactic response to LLC-derived supernatant that contained high concentrations of the chemokine CCL2." (PMID 32038501, 2020). "Indeed, in vitro treatment with CCL2 and CCL5 stimulated neutrophils to kill tumor cells." (PMID 33105656, 2020). "Thus, the inhibition of CCL2 expression by pevonedistat may provide an additional benefit for MPM treatment, in addition to targeting only tumor cells." (PMID 33233664, 2020). "Since tumor intrinsic CCL2 may not be the only relevant source of CCL2, in our study we chose to target the CCL2 receptor, CCR2." (PMID 33247183, 2020). "Therefore, diminishing the CCL2 and CCR2 interaction through the mTOR cascade may reduce TAMs recruitment and chemotaxis, subsequently promoting the anti-tumor effect of CD8+ T cells in TME." (PMID 32483450, 2020). "Of note, an increased expression of IL-17 (IL-17RA), IL-8 (CXCR1) and CCL2 (CCR2) receptors was also observed on M-DM exposed to CM from bcl-2 overexpressing clone, suggesting a larger impact of cancer cell-specific bcl-2 on the interplay between the tumor and the stromal compartment." (PMID 32269145, 2020). "However, BCa patients with a higher tumor stage, higher tumor grade, or metastasis have a significantly higher CCL2 concentration in their urine than patients with a lower tumor stage, with a lower tumor grade, or without metastasis." (PMID 32429318, 2020). "In contrast, the TAM-specific deletion of CCL2 did not impact on the CD8+ T cell tumor recruitment." (PMID 31186412, 2019). "These CAFs express interleukin 6 (IL6), C-C motif chemokine 2 (CCL2), and Transforming Growth Factor Beta 3 (TGFB3) that induce the differentiation of peripheral blood mononuclear cell (PBMC) to MDSC, which contributes to T cell depletion in the tumor microenvironment." (PMID 31416205, 2019). "Nevertheless, the use of either CCL2 or CCR2 inhibitors, in clinical trials, gave disappointing results, indicating the need of supplementary studies considering the presence of potential TME-dependent compensatory mechanisms acting on tumor-resident myeloid cells." (PMID 31447834, 2019). "Furthermore, a number of agents, such as CCL2 inhibitor bindarit, anti-CCL2 mAb carlumab, CSF1 inhibitor GW2580, and dequalinium-14, have been confirmed of potent and sustained anti-tumor activities via declining macrophages infiltration in a battery of cell lines and xenograft models." (PMID 31300030, 2019). "Interestingly, the anti-tumor response to the inhibition of LIF was blunted in the CXCL9−/− mice but not in the CCL2−/− mice." (PMID 31186412, 2019). "CCL-2 released by tumor cells, macrophages, and stromal cells within the TME recruits monocytes that express the receptor CCR-2 and granulocytes (i.e. myeloid-derived suppressor cells; MDSCs) that express the receptor CCR-5 to tumors, thereby driving tumor progression." (PMID 31805946, 2019). "The transcription of Tnfα, Cxcl1, Ccl2, and Ccl20 was upregulated in Spont-PyMT tumors, like in Trans-PyMT ones, even though the fold increases were not always similar in the two tumor types." (PMID 31511510, 2019). "Moreover, significant reduction in tumor size and complete remission have been observed with CCR2b-GD2-CAR T cells and CXCR4-EGFRvIII-CAR NK cells infused in mice bearing CCL2 producing GD2 neuroblastoma or CXCL12 secreting EGFRvIII glioblastoma cells, respectively." (PMID 30420855, 2018). "Moreover, we observed a moderate, yet not significant, induction of CCL2 in most of our tumor cell lines." (PMID 30266096, 2018). "It is also reported that CCL2 and CXCL12 synergistically enhance the in vitro migration of human monocytes and macrophages, suggesting that expression of multiple chemokines in the tumor microenvironment is required for the efficient recruitment of monocytes and TAMs." (PMID 30483271, 2018).
tumor (continued). "Finally, ACKR5/CCRL2, initially described to promote chemotaxis in response to CCL2, CCL5, CCL7, and CCL8, has also been shown to be involved in tumor metastasization, as its expression has been detected in colorectal cancers and even increases in the early phase of liver colonization." (PMID 30591657, 2018). "CCl2 expression in MSCs was shown to be strictly dependent on NICD recruitment at the promoter of CCL2 gene, suggesting that environmental variation of Fbw7 expression might determine the selection of novel Notch-target genes in the tumor microenvironment." (PMID 29996493, 2018). "While naïve neutrophils from FVB mice did not significantly reduce the viability of PyMT tumor cells (p = 0.101), addition of exogenous CCL2 did lead to a decrease in viability of the PyMT cells in this co-culture compared to PyMT cells without neutrophils (p = 0.005)." (PMID 28143493, 2017). "Therefore, the CCL2/CCR2 reaction may have dual context-dependent effects in tumorigenesis: promoting the metastasis of tumors and providing anti-tumor effects at the same time." (PMID 28424406, 2017). "Moreover, addition of CCL2 (50 ng/ml) to co-cultures of naïve neutrophils and 4 T1 cells did not increase the tumor cell killing over that produced by naïve neutrophils without CCL2 addition (Dunn’s test, p = 0.12)." (PMID 28143493, 2017). "Thus, differences in ability to respond to exogenous CCL2 did not result from differences in the levels of CCL2 produced by tumor cells or neutrophils (naïve or TEN) isolated from BALB/c or FVB mice." (PMID 28143493, 2017). "Interestingly, co-culture of naïve or TEN with tumor cells resulted in a decrease in CCL2 in the media as detected by ELISA, but there was an increase in the amount of CCL2 in the cell lysate (data not shown)." (PMID 28143493, 2017). "However, CCL2 did not enhance killing of C57BL/6 TEN neutrophils co-cultured with PyMT tumor cells compared to PyMT plus TEN alone." (PMID 28143493, 2017). "Thus, by secreting remarkable amounts of CCL2 and CCL5, ADSCs that have been recruited into the tumor stroma could promote tumor progression by further increasing the number of TAMs in the tumor microenvironment." (PMID 28545495, 2017). "Because recruitment of TAMs to target vessels to induce vascular permeability requires CCL2 and colony-stimulating factor 1 (CSF1) synthesized by tumor cells to target receptor CCR2 and CSF1R on TAMs, inhibition of CCR2 or CSF1R signaling reduces tumor growth and metastasis." (PMID 28467800, 2017). "Interestingly, we could not detect the classical monocyte attracting chemokine monocyte chemoattractant protein 1 (MCP1 or CCL2), that is overexpressed in several tumor types and correlate to TAM infiltration." (PMID 28759013, 2017). "Moreover, YKL-40 was likely to promote tumor angiogenesis by interacting with syndecan-1 on endothelial cells as well as metastasis by stimulating production of pro-inflammatory and pro-invasive factors such as MMP-9, CCL2 and CXCL2." (PMID 28036271, 2017). "This may activate CCL2/CCR2 signaling pathway and is important in promoting tumor growth." (PMID 28611777, 2017). "We previously demonstrated that intratumoral nitration/nitrosylation of the chemokine CCL2 plays a crucial role in antitumor immunity, since RNS-modified CCL2 restrains T lymphocytes to the stroma at the border of neoplastic lesions, preventing their infiltration to the tumor core." (PMID 26870036, 2016). "Similarly, Ccl2 expression is not decreased in Panc02 tumours implanted in St2−/− and Il33−/− mice compared with those in wt mice as validated by qPCR." (PMID 27150562, 2016). "Ccl2 and Ccl3 mRNA levels were not increased in tumours from HFD mice." (PMID 27708283, 2016). "However, the pro-inflammatory cytokine CCL2 levels were not significantly different in the SG-/- primary tumours compared to SG+/- primary tumours." (PMID 27223472, 2016).
tumor (continued). "Upon tumour antigen pulsing, high levels of chemokines that sustain the recruitment of circulating DCs to inflamed tissues, such as CCL3, CCL4, were expressed, whereas at late time-points constitutive lymphoid chemokine such as CCL2, CCL8, CXCL10, CXCL12 and RANTES were selectively up-regulated." (PMID 26795765, 2016). "Second, the TMA technique only displays a small piece of the original tumor tissue, the information contained may not be typical and the expression of CCL2 and CCR2 is evaluated subjectively." (PMID 27409666, 2016). "Furthermore, the ligands for these receptors (CCL2 and CCL5) are often produced at increased levels by tumor tissues and, as a result, these ligands and their cognate receptors on IM have been targeted as a means to reduce tumor growth." (PMID 27852031, 2016). "Therefore, it is likely that radiation not only induces activation of the STING pathways to activate the Th1/Tc1 T cells but also up-regulates NF-κB to activate CCL2 and CCL5 to attract the activated Th1/Tc1 cells infiltration into the tumor microenvironment to suppress tumor development." (PMID 27014915, 2016). "Likewise, chemokines and cytokines are extensively produced in the tumor microenvironment regardless of the initial triggers, and mediators such as IL-1β, TNFα, CCL2 and IL-6 directly promote tumor progression in experimental models of CRC." (PMID 27494857, 2016). "Moreover, it is also important to establish whether inhibition of CCL2 had distinct effects compared to CCR2 inhibition, and if interference of both can lead to better anti-tumor responses in clinical trials." (PMID 26885690, 2016). "Thus, dl922-947-mediated reduction of CCL2 and IL-8 may have a synergistic effect on TAM depletion by reducing chemokine-induced monocyte recruitment and tumor vasculature." (PMID 26625205, 2016). "In our model, the anti-CCL2 antibody treatment reduces CCL3 expression in MAMs but inhibition rate is only 40% compared with IgG treatment, suggesting that factors other than CCL2 from cancer cells and/or tumor microenvironment also involve in CCL3 secretion from MAMs." (PMID 26275794, 2015). "Thus, we speculate that the ADT-induced production of CCL2 via TNF signaling is a feature of a population resembling PSA−/lo (progenitor) cells, and contributes to the aggressive tumor phenotype of this cancer population, which expands following ADT." (PMID 26327448, 2015). "Using this approach, we found that CCL2 and CXCL2, which are chemotactic for inflammatory monocytes and granulocytes, respectively, were secreted at higher levels by all metastasis-derived cell populations compared to primary tumor explants and the parental cell line." (PMID 25882816, 2015). "Macrophages are among the first immune cells to infiltrate the tumor lesions and then influence the tumor progression/invasion via secretion of several growth factors, cytokines or chemokines, including colony stimulating factor 1 (CSF-1), vascular epithelial growth factor (VEGF) and CCL2." (PMID 25623427, 2015). "The effects of CCL2 blockade on tumor progression were not determined." (PMID 26635798, 2015). "Production of CCL2, which could induce a large amount of accumulation of MDSCs through CCR2, is strongly increased in tumor-bearing mice, and nestin+ splenocytes clearly participate in the increase in chemokine production in tumor- bearing hosts." (PMID 26161081, 2015). "Moreover, the stromal tumor microenvironment that was present in the primary tumor is unlikely to be replicated at the site of the metastatic lesion(s), which lack the cellular interactions that we believe generate CCL2." (PMID 26327448, 2015). "In contrast, CCL2 mRNA was significantly reduced in both data sets, which may reflect induction of CCL2 at the primary tumor site only, rather than also at the metastatic tumor site (see Discussion)." (PMID 26327448, 2015).